INHBA (inhibin subunit beta A)
Diseases named in the same sentence as INHBA in open-access papers (continued):
Sharing a sentence is not in itself a finding about the gene and the disease.
stomach adenocarcinoma (1 paper, 2022). "We also investigated the impact of CAF markers highly clustered with COL1A1 and COL5A1 in correlation analysis, namely THBS2, FAP, INHBA, S100A4, COL11A1, or MMP11, on the outcome of CAF infiltration in stomach adenocarcinoma." (PMID 35739492, 2022).
systemic juvenile idiopathic arthritis (1 paper, 2017). "In systemic juvenile idiopathic arthritis (SJIA), knockdown of miR-146a promoted M1 but diminished M2 SJIA monocytes polarization by targeting INHBA." (PMID 28915705, 2017).
tumor (124 papers, 2007 to 2026). "This elevated INHBA expression was found to be significantly associated with the incidence of tumor lesions, lymph node metastasis, and progression to higher TNM stages." (PMID 41799510, 2026). "Further investigation revealed that INHBA drives malignancy by reprogramming tumor-associated macrophages (TAMs) toward the M2 phenotype in the TME and by inhibiting mitochondrial-dependent ferroptosis in CRC cells." (PMID 41449244, 2025). "Restoring SLC25A10 expression partly reversed the reduced tumor volume and weight caused by INHBA knockdown, whereas silencing SLC25A10 partly attenuated the tumor volume and weight enhancements due to INHBA upregulation." (PMID 41449244, 2025). "Exogenous supplementation with succinate partially reversed the reduction in tumor volume and weight caused by INHBA knockdown." (PMID 41449244, 2025). "To test the relationship between INHBA expression and immune signatures, we analyzed a panel of genes encoding for specific tumor‐infiltrating lymphocyte (TIL) cell types." (PMID 39248018, 2024). "Elucidating tumor-promoting functions of INHBA and their underlying mechanisms is important, because increased expression and elevated circulating Activin-A levels in various cancer types correlate with poor prognosis and with cancer-associated cachexia." (PMID 38304252, 2023). "INHBA, for instance, has been implicated in various cellular processes, including tumor growth and metastasis, making it an attractive candidate for targeted therapies." (PMID 37446311, 2023). "C1QC+ tumor-associated macrophages and INHBA+ monocytes showed a significant reduction in inflammation-related pathways, including the interferon alpha pathway, IL-6 pathway, and interferon gamma pathway." (PMID 36052088, 2022). "Consistently, the EdU and flow cytometry assay revealed that knocking down INHBA mainly reduced the tumor cell proliferation by causing G1/S arrest." (PMID 35236827, 2022). "What's more, the expression of INHBA is significantly associated with tumor lymph node metastasis (TNM) stage 21-24." (PMID 34476008, 2021). "After verification of these genes, 3 hub genes, namely CTHRC1, FNDC1, and INHBA, were found to be upregulated in tumor and associated with poor GC patient survival." (PMID 34968391, 2021). "GSEA and infiltration analysis showed that INHBA expression was significantly associated with tumor progression and some types of immune infiltrating cells." (PMID 35058963, 2021). "INHBA is significantly associated with immune infiltration, especially T cells, which means that INHBA may be involved in tumor immunomodulation." (PMID 36984496, 2023). "However, INHBA perturbation alone has been associated with aggressive tumor behavior, including acceleration of cell proliferation, epithelial mesenchymal transition (EMT), migration and invasion." (PMID 36505394, 2022). "INHBA was found to be associated with tumor lymphatic metastasis." (PMID 35909892, 2022). "Finally, during survival in the tumor microenvironment, macrophages tended to differentiate into two subtypes of M2 macrophages, INHBA+ monocytes and C1QC+ tumor-associated macrophages." (PMID 36052088, 2022). "Animal studies results indicated that INHBA overexpression promoted tumor growth and increased tumor weight and volume." (PMID 41799510, 2026). "Both CLDN1 (p = 2.94 × 10−133) and INHBA (p = 5.52 × 10−19) expressions were significantly up-regulated in a tumor progression-dependent manner." (PMID 40426863, 2025). "In summary, INHBA drives tumor progression by remodeling the immune microenvironment and antagonizing ferroptosis in CRC cells, providing a theoretical basis for developing INHBA-targeted inhibitors or combined immunoferroptosis therapeutic strategies." (PMID 41449244, 2025). "High expression of INHBA in NSCLC was found to be associated with poor differentiation and advanced tumor stage, as well as decreased five-year overall survival." (PMID 41463203, 2025).
tumor (continued). "Consistent with the tumor metastatic analysis, high expression of CLDN1 (hazard ratio (HR) > 1.3; p < 0.01) and INHBA (HR > 1.5; p < 0.001) was associated with poor prognosis, as indicated by a high HR." (PMID 40426863, 2025). "INHBA knockdown notably decreased mtGSH levels in tumor cells, whereas its overexpression elevated mtGSH, as shown by ELISA." (PMID 41449244, 2025). "RT-qPCR showed expression of several macrophage markers in VS of which CD14, ALOX15, Interleukin-1β, INHBA and Colony Stimulating Factor-1R were found to have a high correlation with tumour volume." (PMID 38480935, 2024). "The data indicated that MMA increased the tumor volumes and tumor weights, whereas knocking down INHBA or blockade pathways with SB431542 inhibitor almost abolished the increased tumorigenicity induced by MMA." (PMID 38252148, 2024). "INHBA on SPP1+ macrophages is predicted to interact with ACVR1 on tumor cells, targeting downstream genes, including SERPINE1 and SMAD3, which positively regulate cyclin-dependent protein kinase activity." (PMID 38519500, 2024). "Based on these observations we conclude that INHBA(+) fibroblasts play a role in shaping the tumor immunosuppressive microenvironment by inducing expansion of the pro-tumorigenic CD4( +) CD25(+) FOXP3(+) Tregs." (PMID 38360876, 2024). "Under tumor-containing conditions, the expression of statin βA (INHBA) in lung AMs is up-regulated, thus promoting tumor proliferation and forming a “vicious cycle” in in vivo tumor environment." (PMID 38375207, 2024). "It would be intriguing to look into patient-derived xenografts of INHBA-enriched tumors concurrent to the knockdown of INHBA and ultimately evaluate tumor progression." (PMID 38329386, 2024). "Histological examinations revealed that tumors in mice treated with the Activin A neutralizing antibody displayed notable reductions in tumor size, collagen accumulation, and the presence of INHBA(+) fibroblasts." (PMID 38360876, 2024). "Here, we demonstrated that INHBA expression is highly expressed after a fractionated dose of radiation in all tumor cells, while SERPINE1 expression was highly increased in the cells with knockdown of SOX9 after irradiation." (PMID 38275880, 2024). "Given the functional similarities among the proteins encoded by these genes and the pronounced difference in INHBA expression between tumor and normal tissues, we focused our attention on INHBA." (PMID 39543755, 2024). "Our findings implicated MMA as an oncometabolite of PanNEN progression and innovatively established INHBA as a critical regulator of the tumor progression in PanNENs induced by MMA." (PMID 38252148, 2024). "Subsequently, we reassessed the expression of INHBA, as well as tumor growth and migration/invasion capabilities, using cell proliferation assays, colony formation assays, wound healing assays, and transwell assays." (PMID 39543755, 2024). "Furthermore, bioinformatics analyses revealed a positive association between INHBA expression and the abundance of regulatory T cells (Tregs), myeloid-derived suppressor cells (MDSCs), and Macrophages, which typically play an immunosuppressive role in the tumor microenvironment." (PMID 39543755, 2024). "We uncovered that INHBA associates with a pro-tumor microenvironment by negatively correlating with antitumor CD8+ T and B cells while positively correlating with pro-tumor M1 macrophages." (PMID 38329386, 2024). "Our analysis with mouse primary AM cells indicated that INHBA-expressing AMs in the tumor microenvironment showed reduced expression of a scavenger receptor (macrophage receptor with collagenous structure) compared to the normal counterpart." (PMID 38720352, 2024). "Researchers manifested that INHBA expression was strongly connected with the diameter and invasion of the tumour within gastric malignancy as a sign of poor prognosis." (PMID 39656597, 2024).
tumor (continued). "INHBA, a member of the TGF‐beta superfamily, has been implicated in promoting tumor growth, invasion, and metastasis in various cancers, including CRC." (PMID 39628390, 2024). "Tumor growth of AtT20 xenografts in a mouse subcutaneous model was reduced by continuous therapy with INHBA (activin A)." (PMID 38658971, 2024). "We applied a three-step approach to evaluate a possible regulation of INHBA expression by miRNAs in the primary tumor." (PMID 38329386, 2024). "The expression of INHBA in CC tissue was examined to analyze the relationship between INHBA expression and pathological characteristics, anti-tumor immune response and clinical prognosis of CC, and explore factors affecting the prognosis of CC patients." (PMID 36984496, 2023). "Inhibin beta A (INHBA) expression is upregulated in AMs under tumor-bearing conditions, leading to the secretion of activin A, a homodimer of INHBA." (PMID 36650150, 2023). "The results showed that the positive expression of INHBA was related to the tumor immune infiltration in patients with CC." (PMID 36984496, 2023). "The role of INHBA in OS was investigated by analyzing the correlation between INHBA expression in cancerous tissues and pathological parameters, such as tumor stage." (PMID 37940978, 2023). "INHBA-expressing Tumor cells also increased their expression of Transporter Associated With Antigen Processing (TAP) genes responsible for MHC I antigen loading." (PMID 38304252, 2023). "INHBA mRNA was mainly distributed in the peripheral tumor cells of cancer nests and the stroma of ESCC tissues but was negative in the normal esophageal epithelia and stroma." (PMID 37644505, 2023). "In this study, the expression of INHBA in CC tissue was examined to analyze the relationship between INHBA expression and pathological characteristics, anti-tumor immune response and clinical prognosis of CC." (PMID 36984496, 2023). "The expression of INHBA in lung AMs is upregulated under tumor-bearing conditions, which in turn supports cancer proliferation, constituting a ‘vicious cycle’ in the tumor environment in vivo." (PMID 36650150, 2023). "We also confirmed that activin A, the homodimer of the INHBA subunit, is preferentially produced in tumor-bearing AMs." (PMID 36650150, 2023). "INHBA has a weak significant methylation level change between tumor and normal tissues and mainly enriched in cancer-related signaling pathways." (PMID 37528145, 2023). "The tumor tissues and normal adjacent tissues of patients with CC were collected, and the expression of INHBA in CC tissues and adjacent tissues was detected using immunohistochemistry (IHC)." (PMID 36984496, 2023). "INHBA is a member of the transforming growth factor β (TGF-β) superfamily, which is closely associated with tumor invasion and metastasis." (PMID 37644505, 2023). "In general, abnormally high expressions of INHBA in patients with CC were related to pathological characteristics, anti-tumor immune response and survival time, and lead to a poor prognosis." (PMID 36984496, 2023). "Several studies found that abnormal expression of INHBA exerted various biological functions in different tumor development processes." (PMID 36984496, 2023). "In the present study, we identified INHBA as a direct target of IGF2BP1 with a functional role in tumor invasion induced by IGF2BP1." (PMID 37644505, 2023). "As expected, due to dual inhibition of INHBA expression, the siRNA of INHBA and metformin showed a synergistic effect in inhibiting tumor proliferation." (PMID 35236827, 2022). "The results showed that the mRNA expression of INHBA was consistently higher in tumor tissues than those adjacent tissues and the statistical analysis showed great significance." (PMID 35236827, 2022). "Here, we first identify INHBA as a potential biomarker of prognosis and tumor-infiltrating immune cells." (PMID 36304286, 2022).
tumor (continued). "Then, we analyzed the correlation of INHBA expression with immune infiltrating levels in the tumor microenvironment using Tumor Immune Estimation Resource 2.0 (TIMER2.0) and Gene Expression Profiling Interactive Analysis 2 (GEPIA2)." (PMID 36304286, 2022). "What’s more, in breast cancer patients, the expression of INHBA was positively correlated with tumor-infiltrating Tregs signatures." (PMID 35774793, 2022). "Using a real-time PCR to detect INHBA mRNA expression, we found that INHBA was highly expressed in tumor tissues compared to non-tumor tissues." (PMID 35216189, 2022). "From this clustering, single sample Gene Set Enrichment Analysis (ssGSEA) primarily revealed enriched IL-1 and inflammasome related pathways in NLRP3+ and INHBA+ macrophage populations in the tumor." (PMID 36439171, 2022). "We inferred based on both mRNA and protein that INHBA expression can be used as a biomarker to predict tumor lymphatic metastasis." (PMID 35909892, 2022). "M2-related macrophages, including INHBA+ monocytes and C1QC+ tumor-associated macrophages, were significantly increased in ASPC, following a reduction in juvenile macrophages in the tumor microenvironment (FCN+ monocytes)." (PMID 36052088, 2022). "Third, siRNA-mediated knockdown of INHBA in the tumor fibroblasts resulted in significant FAP gene downregulation (P < 0.001)." (PMID 34642171, 2022). "Because INHBA is a protein secreted into the extracellular space by tumor cells, we applied ELISA to determine its plasma levels." (PMID 35909892, 2022). "We collected 100 CRC tumor tissues and 58 paracancerous tissues to identify the expression level of INHBA." (PMID 35236827, 2022). "Comparison with significantly altered genes in GSE67342 (24 h metformin treatment group) with GSE15781(tumor vs. normal) dataset showed that only INHBA was highly expressed in CRC tumor tissue and simultaneously downregulated after metformin treatment." (PMID 35236827, 2022). "INHBA is associated with the CRC OS rate and plays a role in promoting tumor cell proliferation and migration." (PMID 35909892, 2022). "We observed higher expression of both FAP and INHBA in tumor fibroblasts compared with normal (P < 0.05), and within tumor fibroblasts there was a strong correlation between FAP and INHBA coexpression levels (R = 0.92, P < 0.0001)." (PMID 34642171, 2022). "Among those samples, we found the staining intensity of INHBA in tumor tissues of patients who received metformin treatment was weaker than that of patients treated with other hypoglycemic drugs." (PMID 35236827, 2022). "The expression of CD24 and INHBA was significantly high in tumour tissue (P = 0.0102 and P < 0.001)." (PMID 35999846, 2022). "In the current study, we showed that INHBA silencing reduced tumor growth and migration in BFTC-909 cells." (PMID 35216189, 2022). "Survival analysis of TCGA samples by INHBA levels revealed a significantly poorer survival for tumor samples with high INHBA expression (HR: 0.70; 95% CI, 0.51–0.97, P = 0.029)." (PMID 34642171, 2022). "We selected CESC for further boxplot presentation and confirmed that INHBA expression was upregulated in CESC tumor samples compared to that in normal tissues (p = 0.018)." (PMID 35058963, 2021). "Expressions of INHBA in 275 normal colorectal tissues and 349 tumor tissues were obtained from TCGA." (PMID 34476008, 2021). "In this study, we comprehensively evaluated the difference in INHBA expression between normal and tumor tissues using RNA-seq data from The Cancer Genome Atlas (TCGA) database as well as its association with patient prognosis." (PMID 35058963, 2021). "We performed pan-cancer analyses using the Mann-Whitney U test (Wilcoxon rank sum test) to compare INHBA expression in normal tissues and tumor samples using RNA sequencing data obtained from TCGA and GTEx databases." (PMID 35058963, 2021).